CXCL10 (C-X-C motif chemokine ligand 10)
Diseases named in the same sentence as CXCL10 in open-access papers (continued):
Sharing a sentence is not in itself a finding about the gene and the disease.
tumor (continued). "Furthermore, in vivo neutralization of CXCL10 or CXCL13 dampened the therapeutic effect of abemaciclib, indicating that CXCL10-mediated CD8+T cell infiltration and CXCL13-mediated B cell infiltration paly crucial roles in abemaciclib induced tumor suppression." (PMID 32929370, 2020). "On the one hand, we found that only two hub genes (CXCL10 and ADAM10) had negative associations with tumor purity." (PMID 32206083, 2020). "Loss of function of the PBAF complex increased chromatin reachability to transcription regulator elements of IFN-γ-inducible genes within tumor cells and subsequently increased production of CXCL9/CXCL10 chemokines, allowing more efficient recruitment of Teffs to tumor tissue." (PMID 32850400, 2020). "The staining results showed that CXCL10 was predominately produced from tumor cells rather than from stroma cells." (PMID 32503584, 2020). "This calculation revealed supra-additive upregulation of many of the same cytokines/chemokines in LKB1-reconstituted tumor spheroids co-cultured with MVNs, including CCL2 and CXCL10, while there were some differences such as IL-6, which was amplified, and CCL5, which was suppressed." (PMID 33013881, 2020). "Thus, their corresponding ligands such as CCL5, CXCL9, CXCL10, and CX3CL1 effectively guide CD8+ CTL mobilization from regional lymph nodes to tumor tissues." (PMID 31991604, 2020). "Moreover, examination of cytokine/chemokine production in the tumor microenvironment revealed an increase in the levels of chemoattractive cytokines such as CCL3, CCL4, CCL5, CXCL9, CXCL10 and CXCL11." (PMID 32033490, 2020). "We have observed that CXCL10 secreting CD103+ DC increased in the tumor tissue in an ascending order of nontreated cancer, PDT, FlaB-Vax, and PDT + FlaB-Vax treatments." (PMID 33171765, 2020). "Our data demonstrate that the increase in T cell trafficking into poorly infiltrated tumors following TGFβ blockade may rely on tumor and/or tumor microenvironment expression of CXCR3 ligands: CXCL9, CXCL10, or CXCL11." (PMID 32273499, 2020). "Immunohistochemistry staining showed abundant and uniform expression of CXCL5, CXCL9, and CXCL10 proteins in nontumor adjacent gastric tissues (N), but expression of these proteins was significantly downregulated in all tumor samples (C)." (PMID 33323542, 2020). "A2BR blockade promotes DC activation (e.g., increased CD86 expression on CD11b- DCs), increases CD4+ and CD8+ T cell IFN-γ production, and tumor cell IFN-γ and CXCL10 expression, which supports the therapeutic potential of A2BR antagonists in enhancing antitumor immunity." (PMID 32351498, 2020). "Collectively, we speculate that, in the tumor microenvironment, TILRR can enhance immune infiltration by regulating the CXCL10 and CXCL11 chemokines." (PMID 33031059, 2020). "APOBEC3H was identified to be a potential prognostic predictor and therapeutic target for oncoimmunotherapy in HNSC, in consideration of its essential role in regulating CXCL10-mediated immune activation and CD8+ T cell infiltration into the tumor microenvironment." (PMID 32775421, 2020). "The main population of TAMs comprises CD163+ M2 macrophages, and CD163+ TAMs release soluble (s)CD163 and several proinflammatory chemokines (CXCL5, CXCL10, CCL19, etc.)as a result of TAM activation to induce an immunosuppressive tumor microenvironment together with other immunosuppressive cells." (PMID 32707850, 2020). "TAMs are also able to express immune checkpoint modulators such as PD-L1 and various chemokines (C-C motif chemokine ligand 17 (CCL17), CCL22, C-X-C motif chemokine ligand 10 (CXCL10)) which attract effector/activated T regs that exert an immunosuppressive action and promote tumor growth." (PMID 33375467, 2020). "In contrast, most of the tumor tissues in groups Intralipid-treated, with or without Abraxane treatment, display enhanced positive staining of CXCL10 and iNOS (Fig. 3Bii and iv, Cii and iv)." (PMID 32071352, 2020).
tumor (continued). "Cross-linking and tumour antigen-specific IgE antibody-dependent cellular cytotoxicity (ADCC) of cancer cells by cancer patient-derived monocytes triggered release of pro-inflammatory mediators (TNFα, MCP-1, IL-10, CXCL-10, IL-1β, IL-6, IL-23)." (PMID 33203088, 2020). "In our experience, TME changed towards a more inflamed environment, evidenced by the increase of cytokines like CXCL10 and CCL2, and the decrease of immunosuppressive molecules (like FoxP3 and Nos2), and molecules that promote tumor growth and invasiveness (like IL10 and TGFβ)." (PMID 32064039, 2020). "We also showed that autophagy inhibition could effectively facilitate T lymphocyte migration into the tumor microenvironment by inhibiting the JNK pathway and further inducing the expression of CXCL10." (PMID 32582551, 2020). "Specifically, we again observed CXCL10 and IL-6 production that was significantly higher in co-culture compared to the vasculature alone, regardless of tumor cell STING." (PMID 33013881, 2020). "Moreover, CD103+ cDC1s are a major source of CD8+ T cell chemoattractants, including C-X-C motif chemokine ligand 9 (CXCL9) and CXCL10, in the tumor microenvironment (TME); these chemokines drive T cell recruitment and anti-tumor immunity." (PMID 31947933, 2020). "Additionally, changes in tumor growth and progression after inhibiting BMPER, CXCL10, and HOXA9 expression in the xenografts should also be studied." (PMID 32432046, 2020). "However, similar to the present cellular model, chemokines such as CXCL9, CXCL10, CXCL11 secreted in an autocrine manner by tumor cells were considered to contribute to a pro-tumoral microenvironment." (PMID 30847302, 2019). "The results demonstrated that polyphenols induce CXCR3 expression on regulatory T cells and increases CXCR3 ligands (CXCL9, CXCL10, CXCL11) in tumor microenvironment, it may become an important regulator in the treatment of CRC." (PMID 30973890, 2019). "Additionally, IFN- γ stimulated tumor cells to produce CCL5, CXCL10, and CXCL11, which further supports the notion that DCs will be attracted toward tumor." (PMID 31379812, 2019). "Intratumoral injection of interferon could increase the expression of CXCL-10, CXCL-11, and CCL5 in tumors and help lymphocytes to localize in tumor sites to perform antitumor activities." (PMID 31662753, 2019). "Moreover, tumor-resident cDC1s are the predominant sources of CXCL9 and CXCL10 and mediate recruitment effector T cells into the tumor." (PMID 31143179, 2019). "On the whole, our results provide evidence that the decreased tumor growth, improved CTL response, and decreased neovascularization observed in animals lacking miR-21 in TAMs is mediated, at least in part, by increased IL-12 and CXCL10." (PMID 31710308, 2019). "However, the endothelial progenitor cell (EPC) is mobilized by CXCL10/CXCR3 signaling after small liver grafts, promoting angiogenesis and tumor growth." (PMID 31477121, 2019). "Besides, several chemokines including CXCL9, CXCL10, and CXCL12 were upregulated by genome-wide transcriptional profiling of tumor-infiltrated PTL-CAR-T cells." (PMID 31511513, 2019). "This transformation to “hot tumor” might relate with the expression of IFN-stimulated genes (ISG) such as CXCL9 and CXCL10, which could recruit APC and T cell to tumor." (PMID 30935414, 2019). "Due to the absence of CD103+ DC-derived chemokines, such as CXCL9 and CXCL10, tumor infiltration by CTLs is prevented and antitumor immune responses are impaired." (PMID 31616443, 2019). "It has been shown that murine CXCL10-producing CD103+ DCs are important in effector T-cell navigation to the tumour, and when these cells are no longer present in the TME, an efficient anti-tumour immunity is lacking." (PMID 31091774, 2019). "Collectively, GBE1 prevents CCL5 and CXCL10 secretion in LUAD cells, which may further affect the recruitment of T lymphocytes into the tumor microenvironment." (PMID 31221150, 2019).
tumor (continued). "Although CXCL9 and CXCL10 are described as anti-angiogenic chemokines, their impact on the tumor vasculature under conditions of IL-27 treatment was not tested." (PMID 31637217, 2019). "Further evidence that IR-780 induced a more pronounced effector phenotype was attained by the assessment of multiple CTL effector markers through real-time qPCR of the whole tumor mRNA, demonstrating increased expression of IFN-γ, TNF-α, Granzyme B, EOMES, Perforin, BLIMP-1, FOXO3, and CXCL10." (PMID 31781498, 2019). "Based on previous studies conducted by us and the others, a large number of tumor-infiltrating lymphocytes (TILs) correlates with increased expression of multiple chemokines CCL5 and CXCL10, capable of recruiting effector T cells, by attracting CD8+ T lymphocytes into various tumors." (PMID 31221150, 2019). "CXCL10 having opposing effects on TME that may occur simultaneously, the overall outcome of the disease seems to be tumor-type dependent and thus hard to predict." (PMID 31216755, 2019). "TNF-α and IFN-у appear to enhance eosinophilic production of pro-inflammatory Th1-type chemokines such as CXCL9 and CXCL10 whereas TNF-α and IL-4 stimulate eosinophilic production of Th2-type chemokines, which sustain a more immunosuppressive tumor microenvironment." (PMID 31730503, 2019). "The interaction between CXCL9/CXCL10 with CXCR3 can recruit anti-tumoral dendritic cells, T lymphocytes and natural killer cells to the TME, which could be beneficial for tumor suppression." (PMID 31620367, 2019). "Taken together, our present work indicates that the absence of miR-21 in macrophages favors the formation of a tumor- suppressive microenvironment, characterized by increased expression of IL-12 and CXCL10 that leads to improved CTL response, decreased neovascularization, and decreased tumor burden." (PMID 31710308, 2019). "NK cells play a critical role in anti-tumor immunity and they could respond to several chemokine signals, including CCL3/CCL4/CCL5 via CCR5 and CXCL9/CXCL10 via CXCR340–42." (PMID 30718511, 2019). "The splenic eosinophils in cryo-thermal-treated mice expressed high level of chemokines and pro-inflammatory cytokines (CCL5, CXCL10, IFN-γ, IL-6, IL-12 and IL-15), which could create immunostimulatory microenvironment contributing to anti-tumour immunity." (PMID 31519961, 2019). "A recent analysis of 20 different cytokines and chemokines (some also included here) in culture supernatants harvested from HNSCC tumor tissue-derived cell suspensions, showed, in accordance with the present study, high tumor related levels of CXCL9, CXCL10, and CCL20 and decreased levels of CCL5." (PMID 29587383, 2018). "Thus, the upregulation of such chemokines as CXCL-10 and CXCL-16 is important in the induction of CTL infiltration in the tumor due to radiation." (PMID 30487462, 2018). "Reduced ascites accumulation couldpotentially result from the angiostatic effects of CXCL10, a chemokine that isinduced and released in the TME post-IFN pathway activation via both STING/STAT1 orcould also be due to decreased tumour burden." (PMID 30046165, 2018). "Multiple Th1 cytokines and downstream targets were overexpressed in hot tumours (IFNG, CCL4, CCL5, CXCL9, CXCL10), along with costimulatory and coinhibitory receptors, suggesting these tumours were marked by a state of lymphocyte activation and counter-responses thereto." (PMID 30104673, 2018). "However, when the tumor cells were also stimulated with the type 1 cytokine IFNγ and TNFα an increased expression of CCL2, CCL5, CXCL9, CXCL10 and IL-6 was detected when compared to treatment with the control antibody." (PMID 30192802, 2018). "Moreover, radiation maintains tumor specific molecular immunity and enhances the secretion of tumor cytokines (CXCL9, CXCL10 and CXCL16) to promote tumor immune recognition and T cell infiltration and inducing immunogenic cell death (ICD)." (PMID 29958545, 2018).
tumor (continued). "CXCL9 and CXCL10, agonists of the CXCR3, promote the recruitment of CD4+ Th1 lymphocytes, NK cells, and CD8+ cytotoxic T lymphocytes (CTL) to the TME, where they exert a potent anti-tumor activity." (PMID 30319638, 2018). "The current study shows that CXCR3A and CXCL10 are highly expressed in PTC and in a PTC derived epithelial cell line (TPC-1), consistent with a condition that may favor tumor development and progression." (PMID 29416784, 2018). "We corroborated that MMP-9 cleaves and inactivates key T-cell chemoattractant CXCR3 ligands (CXCL9, CXCL10, and CXCL11) in vitro, and that anti-MMP-9 treatment may contribute to tumor T-cell homing/trafficking via stabilization of CXCL10 in vivo." (PMID 30500835, 2018). "Indeed, Vγ9Vδ2 T lymphocytes were attracted to NB-tumor masses of mice treated with ZOL, where they produced IFN-γ that, in turn, induced CXCL10 expression in NB cells." (PMID 30510968, 2018). "Activated Vγ9Vδ2-T cells may secrete chemokines, such as C-C motif chemokine ligand 3 (CCL3), CCL4, C-X-C motif chemokine 10 (CXCL10), and CXCL13, to recruit αβ-T cells, B cells, NK cells, and macrophages/DCs to the tumor site." (PMID 28894450, 2017). "Intratumoral expression of CXCL9 and CXCL10 was significantly reduced in tumors from compound mutant RasApc mice, but not in single transgenic mice expressing oncogenic KRAS, which display lower tumor number and mortality." (PMID 29163806, 2017). "To test the effects of beta blockers on the chemokine environment in tumors of RRS-exposed animals, we examined the expression of genes that are characteristic of either immune suppression (Foxp3, CCL22) or effector anti-tumor immunity (Granzyme B, CCL5, IFN-γ, CXCL9, CXCL10 and CXCL11)." (PMID 28603578, 2017). "In addition, treatment with HMGN1 and R848 increased CTLs in the draining LNs and upregulated chemokines CXCL9 and CXCL10, as well as IFN-γ, all indicators of Th1 immunity in the tumor tissue." (PMID 28881713, 2017). "Thus, we decided to stain sections with antibodies against CD3, CXCL10, and smooth muscle actin to define the location of CXCL10-producing cells in TLO and tumor areas." (PMID 28567040, 2017). "We have recently shown a strategy to enhance the migration of CXCR3-positive human NK cells to melanoma tumors by stimulating local CXCL10 secretion as CXCR3 ligands are not usually present at the tumor site." (PMID 28923105, 2017). "It is shown that decreased nuclear Ca2+ signaling reduced tumor blood vessel formation and consequentially prevented TNBC growth at least in part due to increased expression of CXCL10, a well-known angiostatic chemokine and a promising target to prevent cancer metastasis." (PMID 28376104, 2017). "In response, local endothelial cells, and potentially the tumor cell itself, could increase local production of CXCL9 and CXCL10." (PMID 28358049, 2017). "Indeed, tumor-homing eosinophils secreted chemoattractants such as CCL5, CXCL9, and CXCL10, which recruited CD8+ T cells to the tumor." (PMID 28791287, 2017). "CXCL10 was distinctive in that no significant increase was observed with age but its parity-dependent tumor response was in the opposite direction with respect to the other cytokines." (PMID 28966800, 2017). "To further understand the role of adaptive immunity in the tumor tissue, we investigated the impact of RRS on tumor weight and on immune suppression markers (Foxp3, CCL22), as well as markers for anti-tumor immunity (Granzyme B, CCL5, IFN-γ, CXCL9, CXCL10 and CXCL11)." (PMID 28603578, 2017). "Additionally, neoplastic cells coexpressed chemokines (CXCL9, CXCL10, GRO, and CXCL12) and their receptors in both tumours." (PMID 28386296, 2017). "Mechanistic studies showed that upon treatment with TheraVac, Hepa1-6-bearing mice generated increased Hepa1-6-specific CTLs in the draining lymph nodes and showed greatly upregulated expression of CXCL9, CXCL10, and IFN-γ and elevated infiltration of T lymphocytes in tumor tissues." (PMID 28881713, 2017).
tumor (continued). "It has been reported that CXCL10 may act in a paracrine fashion affecting the peritumoral CD4+ and CD8+ lymphocytes, and in an autocrine fashion contributing to tumor migration and progression." (PMID 28603578, 2017). "This MDA5-mediated anticancer response requires DC-dependent engulfing of MDA5-activated cancer cells for DC activation and subsequently production of cytokines (CXCL10 and IFN-α) for providing a pro-inflammatory milieu to promote cytolytic activity and IFN-γ secretion of NK cells at the tumor site." (PMID 28216575, 2017). "Stimulation of the cells with 100 ng/ml of the CXCR3 ligands CXCL9 or CXCL10 did not influence tumor cell proliferation." (PMID 28504691, 2017). "Additionally, we found that IR treatment induces an influx of CD8+ T cells into the tumor accompanied by elevated expression of CXCL10 and CCL5 in the tumor, both of which are among the signature genes highly expressed in “T cell-inflamed” tumors." (PMID 27343548, 2016). "Furthermore, αCD40 upregulated IL-2 and the Th1 T cell chemokines, CXCL10 and CXCL11, and increased CD8+ T cell infiltration and tumour PD-L1 expression." (PMID 26918344, 2016). "As assessed by qRT-PCR on tumor fragments, IR treatment increased expression of CXCL10 and CCL5, but not CCL4." (PMID 27343548, 2016). "While this only contained one of our original cell line defined BRCA1/ NFκB target genes (CXCL10) this is not overly surprising as this is a tumour derived classifier." (PMID 26943587, 2016). "Thus, the sunitinib-related inhibition of VEGF signaling results in up-regulation of chemokines CXCL10 and CXCL11 (chemoattractant for T-cells) in tumor vessels." (PMID 27589830, 2016). "Furthermore, analysis of serum samples from MC38 tumour bearing mice also revealed a notable reduction in CCL2 levels, whereas serum levels of CXCL10 and CXCL1 were unaffected." (PMID 26358505, 2015). "CXCL10 is a potent chemokine for the recruitment of CD4+ and CD8+ T cells into the tumor sites." (PMID 25605488, 2015). "Even though the correlations were not significant, it is possible that HO-1, ICAM-1, and CXCL10 play roles in the tumor growth of CRC." (PMID 26087182, 2015). "In accordance with these observations, our experiments performed in the tumor tissue explant model (n = 6 patients), demonstrated that in contrast to BCG, the combination of IFNα and poly-I:C strongly elevated tumor secretion of CXCL10." (PMID 25806105, 2015). "These analyses revealed that the tumours are characterized by expression of inflammatory chemokines (CCL2, CCL5, CCL7, CCL8, CCL12, CXCL9, CXCL10 and CX3CL1), reflected by an enrichment of activated Foxp3− and Foxp3+ T cells expressing T helper type 1-associated chemokine receptors." (PMID 25495686, 2015). "There were also trends toward a positive relationship between tumor volume and HO-1 mRNA expression, and toward a negative relationship between HO-1 mRNA expression and CXCL10 mRNA expression." (PMID 26087182, 2015). "Blockade of key factors in IFN-γ/RANTES defense loop including IFN-γ, IP-10/CXCL10, MIG/CXCL9 and RANTES/CCL5 could accelerate tumor formation and progressive dynamics of PMSB-formulated hosts." (PMID 26512920, 2015). "Further studies showed that the full potency of CCL21-mediated anti-tumor response required the induction of IFN-γ, MIG/CXCL9 and IP-10/CXCL10 in concert, as neutralization or depletion of any one of these cytokines led to a decrease in the frequency of CXCR3+ve T cells and CD11c+ve DC in the tumor." (PMID 24810425, 2014). "DC-CCL21 mediated anti-tumor responses required IFN-γ, MIG/CXCL9, and IP-10/CXCL10." (PMID 24810425, 2014). "Celecoxib treatment reduced CCL2 and increased CXCL10 production, recruiting CTL to the tumor site." (PMID 24202450, 2013). "Tumor rejection and survival was improved compared to mice receiving pulsed DCs or non-pulsed DCs with CXCL10 gene alone." (PMID 24967094, 2013).